USP14 (ubiquitin specific peptidase 14)
Description:
Proteasome-associated deubiquitinase which releases ubiquitin from the proteasome targeted ubiquitinated proteins. Ensures the regeneration of ubiquitin at the proteasome. Is a reversibly associated subunit of the proteasome and a large fraction of proteasome-free protein exists within the cell. Required for the degradation of the chemokine receptor CXCR4 which is critical for CXCL12-induced cell chemotaxis. Also serves as a physiological inhibitor of endoplasmic reticulum-associated degradation (ERAD) under the non-stressed condition by inhibiting the degradation of unfolded endoplasmic reticulum proteins via interaction with ERN1. Indispensable for synaptic development and function at neuromuscular junctions (NMJs) (By similarity). Plays a role in the innate immune defense against viruses by stabilizing the viral DNA sensor CGAS and thus inhibiting its autophagic degradation. Inhibits OPTN-mediated selective autophagic degradation of KDM4D and thereby negatively regulates H3K9me2 and H3K9me3.
Synonyms: TGT; Ubp6
Tractability: Small molecule: a structure with a bound ligand is known; it has a binding pocket of medium quality. Antibody: UniProt places it where antibodies can reach, with high confidence; its Gene Ontology location is reachable by antibodies, with high confidence; the Human Protein Atlas places it where antibodies can reach. PROTAC: ubiquitination databases record sites on it; its protein half-life has been measured; a small molecule that binds it is known.
Target class: Cysteine protease; Cysteine protease CA clan; Protease; Enzyme; Cysteine protease C19 family
Gene: Protein-coding gene on chromosome 18 (158,351 to 214,629, forward strand). Ensembl gene ENSG00000101557.
Subcellular location: Cytoplasm; Cell membrane
Subcellular location (Human Protein Atlas): Cytosol; Plasma membrane; Endoplasmic reticulum
Pathways (Reactome):
Immune System: Regulation of NF-kappa B signaling
Metabolism of proteins: Ub-specific processing proteases
Gene Ontology:
Molecular function: cysteine-type deubiquitinase activity; deubiquitinase activity; endopeptidase inhibitor activity; K63-linked deubiquitinase activity; proteasome binding; protein binding; cysteine-type endopeptidase activity
Biological process: inflammatory response; negative regulation of ERAD pathway; negative regulation of ubiquitin-dependent protein catabolic process; protein K48-linked deubiquitination; regulation of chemotaxis; regulation of proteasomal protein catabolic process; proteasome-mediated ubiquitin-dependent protein catabolic process; protein deubiquitination
Cellular component: cell surface; cytoplasm; cytoplasmic vesicle; cytosol; extracellular exosome; plasma membrane; glutamatergic synapse; presynaptic cytosol; synapse
Genetic constraint (gnomAD): Loss-of-function variants: 21 observed, 48.21 expected, observed/expected ratio (o/e) 0.44, 90% interval 0.31 to 0.63. The upper end of that interval is the gene's LOEUF score, 0.63, which puts it in group 2 of 6, group 1 being the genes least tolerant of losing a copy. Missense variants: 349 observed, 461.35 expected, observed/expected ratio (o/e) 0.76, 90% interval 0.69 to 0.83. Synonymous variants: 152 observed, 156.27 expected, observed/expected ratio (o/e) 0.97, 90% interval 0.85 to 1.11.
Homologues: Orthologues: chimpanzee USP14 (99% identical), macaque USP14 (99% identical), dog USP14 (99% identical), pig USP14 (99% identical), guinea pig USP14 (98% identical), mouse Usp14 (97% identical), rat Usp14 (97% identical), rabbit USP14 (88% identical), tropical clawed frog usp14 (86% identical), zebrafish usp14 (81% identical), Drosophila melanogaster Usp14 (54% identical), Caenorhabditis elegans usp-14 (43% identical). Paralogues in human: USP11 (23% identical), USP32 (23% identical), USP8 (23% identical), USP19 (22% identical), USP15 (22% identical), USP4 (22% identical), USP9X (22% identical), USP37 (21% identical), USP38 (21% identical), USP9Y (21% identical), USP24 (20% identical), USP6 (20% identical), and 59 more.
Diseases named in the same sentence as USP14 in open-access papers:
USP14 is named in the same sentence as 130 diseases in open-access papers, as found by Europe PMC text mining. Sharing a sentence is not in itself a finding about the gene and the disease. The quoted sentences say what the papers report.
breast carcinoma (28 papers, 2017 to 2025). "Given the role of USP14 as potential target for breast cancer therapy, the molecular disease-causing mechanisms of USP14 were investigated." (PMID 35069211, 2021). "More specifically, the increased expression of USP14 among patients with breast cancer was closely associated with poor prognosis." (PMID 35069211, 2021). "The combining effects of enzalutamide and USP14 inhibition on breast cancer cell proliferation and apoptosis and associated cell signaling were evaluated in vitro and in vivo." (PMID 31126320, 2019). "USP14 was reported to be associated with PSMD2 in breast cancer and it is considering as a major regulator of proteasome by ubiquitin chain disassembly." (PMID 31013812, 2019). "USP14 is closely associated with the occurrence and development of multiple malignant tumors, such as breast cancer, lung adenocarcinoma, multiple myeloma and other tumors." (PMID 30319415, 2018). "Aberrant expression of USP14 is associated with progression of various cancers, including colorectal carcinoma 26, hepatocellular carcinoma 44, pancreatic ductal adenocarcinoma 27, breast cancer 45, and gastric cancer." (PMID 39990235, 2025). "USP14 depletion accelerated K48-linked ubiquitination and reduced the stability of the AR protein, which further suppressed the proliferation of AR-responsive breast cancer cells." (PMID 35906484, 2023). "Recent studies reported that USP14 removes the ubiquitin on androgen receptors in prostate and breast cancer cells to promote cell growth." (PMID 38909015, 2024). "Previous investigations demonstrate USP14’s involvement in the progression of breast cancer by influencing key processes such as proliferation, invasion, and apoptosis." (PMID 38383348, 2024). "Differential expression analysis was also performed using TCGA database, which showed significant overexpression of USP14 in tumors such as breast cancer(BRCA), and liver cancer(LIHC) compared to normal tissues." (PMID 38383348, 2024). "Inhibition of USP14 resulted in suppressed AR-responsive (AR+) breast cancer cell proliferation by G0/G1 cell cycle arrest." (PMID 35884607, 2022). "In breast cancer cells, knocking down USP14 reduced the protein expression of CDK1 by increasing the ubiquitination level, thereby arresting the cell cycle in the G2/M phase, and significantly reducing cell proliferation." (PMID 35549778, 2022). "In AR+ breast cancer cells, USP14 inhibition can induce poly (ADP-ribose) polymerase 1 (PARP) cleavage and suppress BCL2 protein expression." (PMID 35884607, 2022). "Both genetic knockdown and pharmacological inhibition of USP14 inhibits the proliferation and induces the apoptosis of AR-positive breast cancer cells." (PMID 35069211, 2021). "Mechanistically, USP14 controls cell cycle progression through deubiquitination of CyclinB1, which functions as a crucial indicator predictive of the survival in ER+ breast cancer." (PMID 34575114, 2021). "USP14 has been extensively studied because of its overexpression in lung cancer, breast cancer, ovarian cancer, and oesophageal squamous cell carcinoma." (PMID 34179009, 2021). "Elevated expression of USP14 has been observed in breast cancer tissues and the level of USP14 is inversely relevant to long-term survival." (PMID 34575114, 2021). "In recent studies, the use of IU1 to inhibit USP14 enhanced the growth inhibition and apoptosis of breast cancer cells by enzalutamide." (PMID 34179009, 2021). "A growing body of evidence has suggested that USP14 contributes to the occurrence and development of breast cancer." (PMID 35069211, 2021). "In our previous researches, we have been explored the effect of USP14 on the growth of prostate cancer and breast cancer cells via regulating the stability of AR." (PMID 34548474, 2021). "USP14 is required for enhancing AR+ breast cancer cell proliferation through deubiquitination and stabilization of AR." (PMID 34575114, 2021).
breast carcinoma (continued). "USP14 inhibition combined with the drug enzalutamide enhanced the sensitivity of breast cancer compared with single-drug treatment." (PMID 33158118, 2020). "It has been reported that AR can be stabilized by USP14, and depletion of USP14 reduces cell proliferation by blocking the G0/G1–S phase transition in AR-responsive breast cancer cells." (PMID 32268558, 2020). "In summary, this study demonstrates a potential advantage of enzalutamide in combination of USP14 inhibition in AR-positive breast cancer treatment, compared with the treatment with each alone." (PMID 31126320, 2019). "We have reported that USP14 mediates deubiquitination and stabilization of the AR in prostate and breast cancer cells." (PMID 31126320, 2019). "In the present study, we evaluated the effects of enzalutamide combined with USP14 inhibitor IU1 or with USP14 siRNA on breast cancer in vitro and in vivo." (PMID 31126320, 2019). "Collectively, our data suggest that USP14 inhibition in combination with enzalutamide represents a potentially new therapeutic strategy for breast cancer." (PMID 31126320, 2019). "Lastly, we tested the antitumor activity of the co-treatment of enzalutamide and IU1/USP14 knockdown in nude mice bearing tumor xenografts from MCF-7 breast cancer cells." (PMID 31126320, 2019). "Silencing or inhibiting USP14 triggers cell growth inhibition and cell cycle arrest by decreasing AR level in AR-positive breast cancer cells." (PMID 31126320, 2019). "To explore the relationship between USP14 and AR, we analyzed the expression levels of USP14 in AR positive breast cancer." (PMID 31126320, 2019). "The current study aims to explore the anticancer effect of a treatment combining AR antagonist enzalutamide with USP14 inhibition on breast cancer cells." (PMID 31126320, 2019). "USP14 inhibition via administration of IU1 or USP14-specific siRNA/shRNA enhanced cell growth inhibition and apoptosis induction by enzalutamide in breast cancer cell lines in vitro and in vivo." (PMID 31126320, 2019). "Evidence suggests that USP14 is over-expressed in breast cancer tissue compared to adjacent normal tissue; evidence also reveals that over-expression of USP14 in breast cancer patients is tightly correlated to poorer overall survival and prognosis." (PMID 30319415, 2018). "The downregulation of USP14 significantly inhibited breast cancer cell proliferation and metastasis." (PMID 29326710, 2017). "Furthermore, both genetic and pharmacological inhibition of USP14 significantly suppressed the growth of AR-reactive breast cancer cells by impeding the G0/G1-S phase transition and inducing apoptosis." (PMID 38383348, 2024). "PSMD2 physically interacts with p21 and p27 and mediates their degradation via the ubiquitin-proteasome pathway by cooperating with the deubiquitinating enzyme USP14, subsequently promoting cell proliferation and facilitating cell cycle progression in breast cancer." (PMID 37875476, 2023). "In addition, USP14 was reprorted to be ectopically expressed in various cancer types, including bladder cancer, lung cancer, breast cancer, and PDAC." (PMID 35906484, 2023). "Inhibiting USP14 could trigger autophagy via ER stress-mediated UPR in lung cancer; moreover, USP14 deubiquitinates CDK1 in breast cancer to promote its cell cycle." (PMID 37686660, 2023). "USP14 plays an anti-apoptotic role in breast cancer via AR deubiquitination." (PMID 35884607, 2022). "Ubiquitin-specific protease 14 (USP14) is DUB family protein that reversibly associates with the 19S regulatory particle 54 and was shown to participate in the progression of multiple tumor types, including breast cancer 55-57." (PMID 35414770, 2022). "Moreover, USP14 expression has a positive correlation with AR expression according to the results from the TCGA database, and is remarkably high in all subtypes of breast cancer." (PMID 34575114, 2021).
breast carcinoma (continued). "It has been demonstrated that inhibition of USP14-mediated androgen receptor (AR) deubiquitination contributes to the downregulation of AR proteins and suppression of AR-related signaling pathways, such as Wnt/β-catenin in breast cancer." (PMID 33791305, 2021). "As USP14 has been reported to be essential for breast cancer cell growth through the degradation of AR, it might be feasible to treat AR-positive breast cancer via the inhibition of USP14." (PMID 35069211, 2021). "USP14 inhibition induced cell cycle arrest and apoptosis and overexpression of AR abrogated significantly the antiproliferative effect induced by USP14 siRNA in AR+ breast cancer cells." (PMID 31126320, 2019). "We have previously reported that deubiquitinase USP14 stabilizes AR proteins by deubiquitination and USP14 inhibition results in inhibition of cell growth and tumor progression in AR-positive prostate cancer and breast cancer." (PMID 31126320, 2019). "Thus, we tested the combination effect of an AR antagonist (enzalutamide) and USP14 inhibitor (IU1)/siRNA in breast cancer cells." (PMID 31126320, 2019). "We have demonstrated that enzalutamide and USP14 inhibition synergistically inhibit cell viability in breast cancer cells; this combined growth inhibition effect of the two agents is predominantly due to more effective induction of cell cycle arrest and cell apoptosis." (PMID 31126320, 2019). "Therefore, we predicted that a treatment combining enzalutamide and USP14 inhibition should be more effective than the treatment with either single agent in terms of suppressing AR signaling in AR-positive breast cancer cells." (PMID 31126320, 2019). "The results show a statistically significant positive correlation between USP14 expression and AR expression in breast cancer, suggesting that the increased USP14 expression might have resulted from elevated AR expression." (PMID 31126320, 2019). "However, the precise molecular mechanisms by which USP14 interacts with PBX3 in breast cancer remain unclear." (PMID 35414770, 2022). "Thus, USP14 promotes resistance to enzalutamide in AR+ breast cancer." (PMID 34575114, 2021). "Therefore, USP14-targeted inhibition in combination with the enzalutamide AR antagonist might represent a potential therapeutic strategy for breast cancer therapy." (PMID 35069211, 2021). "Hence, the synergy between enzalutamide and USP14 inhibition in antitumor effect on breast cancer also may be attributable to additional tumor suppressing actions from USP14 inhibition, beyond suppressing AR signaling." (PMID 31126320, 2019). "Moreover, USP14KD human breast carcinoma MDA-MB-231 cells and USP14KD human hepatic adenocarcinoma SK-HEP-1 cells showed increased cell migration and invasion, indicating that USP14 is negatively implicated in the cancer progression by the inhibition of autophagy induction." (PMID 29326710, 2017). "The therapeutic effects of DUB inhibitors such as USP1, USP4, USP7, USP14 and USP33 have been confirmed in prostate cancer, lung cancer, breast cancer and hematological malignancies." (PMID 34179009, 2021). "In LNCaP, MCF7 (human breast cancer cell), and A549 cell (human lung cancer cell), endogenous FASN protein levels were increased by USP14 knockdown contrary to the results in MPHs." (PMID 34948233, 2021). "To assess the antiproliferative effects of enzalutamide in different doses, alone or in combination with USP14 specific inhibitor IU1 on breast cancer cells, we used an MTS assay to test cell viability on a panel of 5 breast cancer cell lines." (PMID 31126320, 2019).
breast carcinoma (continued). "We established stable USP14 knockdown cancer cells, USP14KD human breast carcinoma MDA-MB-231 (USP14KD MDA-MB-231), and human hepatic adenocarcinoma SK-HEP-1 cells (USP14KD SK-HEP-1)." (PMID 29326710, 2017). "Moreover, cellular data demonstrated that knocking down USP14 inhibited the proliferation and metastasis of the MDA-MB-231 breast cancer cell line instead of promoting its apoptosis." (PMID 35069211, 2021). "Moreover, b-AP15, PtPT, and VLX1570, as inhibitors of ubiquitin-specific protease 14 (USP14) and UCHL5, induce apoptosis in myeloma, breast cancer, and prostate cancer cells." (PMID 32596150, 2020). "Importantly, the synergy in in the cytostatic effect on breast cancer cells between enzalutamide and IU1 or USP14 knockdown observed in cell cultures has been confirmed by our mouse xenograft experiments." (PMID 31126320, 2019). "Although the USP14/UCHL5 DUB inhibitor b-AP15 induced anti-tumor response in several types of malignant tumor including colorectal cancer, myeloma and breast cancer, its effect on human prostate cancer cells, especially the castration-resistant prostate cancers (CRPC), is undefined yet." (PMID 28968984, 2017). "However, no prior reported study has investigated whether USP14 inhibition in combination with AR antagonization has a benefit in treating breast cancer." (PMID 31126320, 2019).